RYR1 (ryanodine receptor 1)
Diseases named in the same sentence as RYR1 in open-access papers (continued):
Sharing a sentence is not in itself a finding about the gene and the disease.
Duchenne muscular dystrophy (8 papers, 2012 to 2023). Duchenne muscular dystrophy (DMD) is a neuromuscular disease characterized by rapidly progressive muscle weakness and wasting due to degeneration of skeletal, smooth and cardiac muscle. "Here we focus on primary RyR1 mutation-related myopathies, as well as considering Duchenne muscular dystrophy (DMD), a disease with a secondary involvement of RyR1." (PMID 26793121, 2015). "S107 fixes Ca2+ leak via RyR1 and improves exercise capacity in aging and may represent a new therapeutic approach for Duchenne muscular dystrophy." (PMID 35399287, 2022). "A common underlying abnormality in calcium handling indicates that pharmacological targeting of dysfunctional RyR1 could be a novel therapeutic approach to improve muscle function in Limb-Girdle and Duchenne muscular dystrophies." (PMID 22640601, 2012). "Proteins involved in redox regulation represent hallmarks and potential therapeutic targets in several early-onset myopathies, including RYR1- and SEPN1-related myopathies, and in Duchenne muscular dystrophy (DMD)." (PMID 34205993, 2021).
distal myopathy (7 papers, 2017 to 2022). Distal myopathy refers to a group of muscle diseases which share the clinical pattern of predominant weakness and atrophy beginning in the feet and/or hands. "For example, three different RYR1 mutations were identified in calf-predominant distal myopathy, a mild dominant distal myopathy characterized by fatty degeneration of medial gastrocnemius, elevated creatine kinase levels, and the presence of cores in muscle biopsies." (PMID 35980353, 2022). "It has been reported that multicore‐like unevenness of stain could occasionally occur in patients with distal myopathy caused by RYR1 mutations." (PMID 34170073, 2021). "In addition, a sporadic case with a missense RYR1 mutation was reported to exhibit an adult‐onset, anterior tibial muscle‐prominent distal myopathy with multiple cores pathology." (PMID 34170073, 2021). "Here we describe a patient with distal myopathy found to be a compound heterozygous for a novel pathogenic variant in RYR1 and an additional missense variant of unknown significance in the same gene, expanding the spectrum of RYR1‐related myopathy." (PMID 29178655, 2017). "Two siblings, P63-Myo142 and P64-Myo142.1, presenting with lower leg distal myopathy, with biopsy and MRI findings matching the genotype, were heterozygous for RYR1:NM000540.2: c.14209C > T; p.(Arg4737Trp)." (PMID 35741838, 2022). "We expand the spectrum of RYR1‐related myopathy with the description of a novel phenotype in an adult patient presenting with hand weakness and suggest considering RYR1 analysis in the diagnosis of distal myopathies." (PMID 29178655, 2017).
periodic paralysis (7 papers, 2018 to 2024). "A strong connection between PP, RyR1 channels and mitochondria is suggested by the fact that RyR1 and mitochondrial mutations have been reported to exhibit an atypical periodic paralysis phenotype and coenzyme Q10, an electron carrier between respiratory chain enzymes, was effective in treating PP." (PMID 39777323, 2024). "Furthermore, missense mutations in Ryanodine receptor type 1 (RYR1), which promotes release of calcium within myofibrils, were recently identified in patients with periodic paralysis." (PMID 35158718, 2022). "Moreover, RYR1 mutations can also result in episodic manifestations of malignant hyperthermia syndrome (MHS), exertional rhabdomyolysis and periodic paralysis." (PMID 31874912, 2019).
Respiratory insufficiency (7 papers, 2007 to 2024). "Two individuals with dominant RYR1 variants exhibited respiratory insufficiency: a clinical symptom more commonly associated with recessive RYR1-RM cases." (PMID 29556213, 2018). "Management is mainly supportive and has to address the risk of marked respiratory impairment in SEPN1-related MmD and the possibility of malignant hyperthermia susceptibility in RYR1-related forms." (PMID 17631035, 2007).
skeletal myopathies (7 papers, 2016 to 2025). "It is well documented that leaky RyR1 channels are associated with skeletal myopathies such as CCD and MH." (PMID 29278865, 2018). "The calcium channel RYR1 is associated with skeletal myopathies and malignant hyperthermia, but primum atrial septal defects in one mouse allele suggest a role in early cardiac development." (PMID 27058611, 2016). "Taken together, our findings emphasize the critical role of the EF hand-S2–S3 loop interaction in Ca2+/Mg2+-dependent inhibition of RyR1 and provide insights into potential therapeutic strategies targeting this domain interaction for the treatment of skeletal myopathies." (PMID 38159862, 2023).
External ophthalmoplegia (6 papers, 2007 to 2024). Paralysis of the external ocular muscles. "The three newly solved cases included one patient with a typical autosomal recessive RYR1-associated myopathy, and a patient with chronic progressive external ophthalmoplegia and late-onset parkinsonism who had a likely pathogenic POLG variant." (PMID 38127101, 2024). "Multiminicore myopathy due to recessive mutations in RYR1 presents generally in infancy with external ophthalmoplegia, limb weakness, and wasting of hip girdle muscles similar to central core disease." (PMID 33827624, 2021). "However, MmD-associated recessive RYR1 mutations give rise to clinical features such as external ophthalmoplegia, bulbar involvement and a moderate degree of respiratory impairment not commonly observed in typical dominant CCD." (PMID 17631035, 2007). "Mutations in RYR1 may cause autosomal recessive or autosomal dominant central core disease, autosomal recessive minicore myopathy with external ophthalmoplegia, and autosomal recessive or autosomal dominant neuromuscular disease, congenital, with uniform type 1 fiber." (PMID 33827624, 2021).
multiple pterygium syndrome (6 papers, 2014 to 2022). "In 2016, Lethal multiple pterygium syndrome (LMPS) was considered at the extreme end of the RYR1-RD spectrum." (PMID 36131268, 2022).
ptosis (6 papers, 2022 to 2025). The drooping of the upper eyelid. "Ptosis, facial muscles and ophthalmoplegia/paresis, for example, were described in patients with an Ryr1 mutation, although these symptoms were described as more frequent in recessive cases than in dominant/de novo cases." (PMID 36498898, 2022). "Even though the proband did not carry additional variants in genes related to MH, he had some features that could be found in recessive RYR1 mutations, such as facial dysmorphism, strabismus, ptosis, joint hyperlaxity, muscle hypotrophy, and increased nuclear centralization." (PMID 37510264, 2023).
congenital muscular dystrophy (5 papers, 2013 to 2024). A muscular dystrophy that is characterized by diminished muscle tone (hypotonia), progressive muscle weakness and degeneration (atrophy), abnormally fixed joints, spinal rigidity, and delays in reaching motor milestones such as sitting or standing unassisted. "Causative variants were found in nine patients with congenital muscular dystrophy in the ACTA1 gene (in one patient), GFPT1 (in one patient), PIGY (in two patients), POMT1 (in one patient), MCU1 (one patient), RYR1 (one patient), and TTN (one patient)." (PMID 37989827, 2024). "There was also no increase in fat and connective tissue, a feature which is common in severe early-onset RYR1-related myopathies that may occasionally mimic a congenital muscular dystrophy, and may also relate to the part of the quadriceps sampled because of differential muscle involvement." (PMID 30788618, 2019). "Thirteen were diagnosed with CCD, 7 with MmD, 8 with non-specific histological features (classified as RYR1-related myopathy or RRM), and 1 with congenital muscular dystrophy." (PMID 23919265, 2013).
Heat Stroke (5 papers, 2017 to 2024). A condition caused by the failure of body to dissipate heat in an excessively hot environment or during PHYSICAL EXERTION in a hot environment. "What is less well recognized is the risk of exertional hyperthermia and possible heat stroke in individuals who have RYR1 pathogenic variants." (PMID 28361098, 2017). "(2016), of the 23 individuals in a military cohort who had well‐documented episodes of exertional heat stroke, three of them (13%) had a pathogenic RYR1 variant." (PMID 28361098, 2017). "In addition, the susceptibility to exertional heat stroke is related to the mutation of the RYR1 gene." (PMID 38463518, 2024). "We show here that an oxolinic acid-derivative RyR1-selective inhibitor, 6,7-(methylenedioxy)-1-octyl-4-quinolone-3-carboxylic acid (Compound 1, Cpd1), effectively prevents and treats MH and heat stroke in several mouse models relevant to MH." (PMID 34257294, 2021). "Here, the authors show that an oxolinic acid-derivative RyR1 inhibitor effectively prevents and treats MH and heat stroke in various MH mouse models." (PMID 34257294, 2021). "The YS mutation enhances both the sensitivity of RyR1 to activators (e.g. DHPR, caffeine, 4-chloro-m-cresol) and the temperature-dependence of RyR1 Ca2+ leak, alterations that underlie the MH susceptibility and exertional heat stroke phenotypes of these mice." (PMID 32223895, 2020).
respiratory failure (5 papers, 2014 to 2021). The significant impairment of gas exchange within the lungs resulting in hypoxia, hypercarbia, or both, to the extent that organ tissue perfusion is severely compromised. "These mice, with an autosomal recessive RYR1‐RM disease presentation, showed a phenotype of reduced muscle mass, and indeed were paralyzed from birth, eventually dying of respiratory failure and asphyxia." (PMID 34528764, 2021). "Mouse knock-out experiments have shown that RyR1 and RyR2 have a critical role in physiology and development: mice deficient in RyR1 died perinatally due to respiratory failure while those lacking RyR2 died during the early stages of embryonic development." (PMID 32899693, 2020). "Clinical features: Overlapping with other recessive RYR1-RM, RYR1-related CFTD clinical presentations include prominent hypotonia and weakness of axial muscles, myopathic facies, respiratory failure, feeding difficulties, and ophthalmoparesis." (PMID 30406384, 2018). "Recessively inherited or de novo dominant RYR1-related CCD present with more severe features such as fetal akinesia syndrome (severe hypotonia, multiple arthrogryposis, respiratory failure)." (PMID 30406384, 2018).
Alzheimer disease (4 papers, 2016 to 2023). A progressive, neurodegenerative disease characterized by loss of function and death of nerve cells in several areas of the brain leading to loss of cognitive function such as memory and language. "For example, pathogenic Ca2+ dysregulation is linked with RyR1 alterations in Alzheimer’s disease, mutant protein-induced mitochondrial dysfunction in Huntington’s disease, and sarcolemma fragility in dystrophinopathies." (PMID 28330496, 2017).
Brody myopathy (4 papers, 2009 to 2023). Brody myopathy is a hereditary condition that affects the skeletal muscles (muscles used for movement). "The clinical manifestations, genetic patterns, and prevalence of myopathies vary in Brody myopathy and RYR1 mutation-associated myopathies, whereas an exon group analysis of a malignant hyperthermic family reported that all members of the family had ATP2A1 deletion of Brody myopathy." (PMID 35692882, 2022). "Since our affected siblings shared disease-associated mutations in RYR1 and ATP2A1, and the index case was diagnosed as MHS after postoperative rigidity, we considered the possibility that this family is affected with two different coexisting diseases, MH and Brody myopathy." (PMID 25614869, 2014). "Therefore, because ATP2A1 and RYR1 are required to temporally coordinate calcium concentration, zebrafish ryr1b mutants might provide a useful model for Brody myopathy and MmD." (PMID 19956802, 2009).
dystrophinopathies (4 papers, 2017 to 2021). "Altogether, our study emphasizes the key role of RYR1-mediated intracellular Ca2+ mishandling in myogenic differentiation (and to some extent in the motor outcome) in DMD and the potential value of RYR stabilizers as adjunctive therapy in human dystrophinopathies." (PMID 34884796, 2021).
hypospadias (4 papers, 2018 to 2023). Hypospadias is the displacement of the urethral meatus on the ventrum of the penis. "In this study, we aim to explore the relationship between the C6487T polymorphism in the RYR1 gene and the risk of congenital hypospadias among Chinese children." (PMID 30027098, 2018). "Given the fact that replication is a major issue in genetic studies, we suggest that more prospective studies with larger sample size be conducted to confirm the effects of RYR1 C6487T polymorphisms on congenital hypospadias." (PMID 30027098, 2018). "Herein, we evaluated the correlations of RYR1 C6487T polymorphism with the risk and severity of hypospadias." (PMID 30027098, 2018). "Collectively, we innovatively explored the relationship between RYR1 C6487T polymorphisms and congenital hypospadias and further investigated more valuable diagnostic indicators to provide possible therapies for the disease." (PMID 30027098, 2018). "The results indicated patients carrying CT, TT genotypes, and T allele of RYR1 C6487T polymorphism may increase the incidence of congenital hypospadias." (PMID 30027098, 2018). "Our results displayed that RYR1 C6487T polymorphism may be associated with the susceptibility to congenital hypospadias." (PMID 30027098, 2018). "Our study demonstrated that RYR1 C6487T polymorphism might be associated with an increased risk of congenital hypospadias in Chinese Han children." (PMID 30027098, 2018). "In summary, our study suggests that RYR1 C6487T polymorphism may contribute to the risk of congenital hypospadias." (PMID 30027098, 2018). "More importantly, we cannot clarify how the function of RYR1 is linked to the development of hypospadias and what may be the causal variant underlying the association." (PMID 30027098, 2018). "We measured the polymorphism of RYR1 C6487T by using polymerase chain reaction-restriction fragment length polymorphism and analyzed different genotypes and allelic genes to explore their associations with the risk of congenital hypospadias." (PMID 30027098, 2018). "The polymorphism of RYR1 C6487T in the peripheral blood was detected by polymerase chain reaction-restriction fragment length polymorphism, and different genotypes and allelic genes were analyzed to explore their associations with the risk of congenital hypospadias." (PMID 30027098, 2018). "This was associated with increased mRNA expression of Ca2+ channels important in regulating VSMC Ca2+ influx, specifically CACNA1C (P = 0.03), IP3R (P = 0.007), TRPM2 (P = 0.001), SERCA (P = 0.008), and RyR1 (P = 0.01) in boys with hypospadias vs. controls." (PMID 35567552, 2022). "Another study found that the distribution frequency of CC/CT/TT genotypes in the ryanodine receptor 1 (RYR1) gene was significantly different between patients with mild hypospadias in comparison to patients with moderate to severe hypospadias." (PMID 32391298, 2020). "With congenital hypospadias as the dependent variable and premature birth, ectopic pregnancy, low birth weight, and RYR1 C6487T served as independent variables for logistic regression analysis to identify the risk factors of congenital hypospadias." (PMID 30027098, 2018). "However, since RYR1 was not implicated in hypospadias etiology before, our findings are potentially important." (PMID 30027098, 2018).
myasthenia gravis (4 papers, 2016 to 2023). Myasthenia gravis (MG) is a rare, clinically heterogeneous, autoimmune disorder of the neuromuscular junction characterized by fatigable weakness of voluntary muscles. "Finally, in about 54% of seronegative Myasthenia Gravis patients, anti-RyR1 (ryanodine receptor type 1)-antibodies can be detected." (PMID 36499379, 2022).
arrhythmogenic right ventricular cardiomyopathy (3 papers, 2018 to 2023). "The most frequent in the ACMG SFs were gene/disease and frequency TTN DCM (four times); KCNQ1 LQTS (three times); MYBPC3 HCM (two times); TMEM43 arrhythmogenic right ventricular cardiomyopathy (two times); PALB2 HBC (two times); and RYR1 MH (two times)." (PMID 36635046, 2023).
arthrogryposis (3 papers, 2015 to 2025). A rare, non-progressive congenital disorder characterized by multiple joint contractures which are present at birth. "Two families presenting with a current at-risk pregnancy were then studied prospectively, and a molecular genetic diagnosis was obtained in both families through the identification of GLE1 and RYR1 variants causing a severe form of fetal akinesia syndrome with arthrogryposis." (PMID 24961629, 2015). "Therefore, even in a case of congenital multiminicore myopathy associated with arthrogryposis and mutation absence in the RYR1, or even genes involved in congenital myasthenia or myopathy, analysis of the TTN gene and, in particular, MTT-only exons is highly recommended." (PMID 39684706, 2024). "None of the individuals with arthrogryposis caused by pathogenic variants in COL6A1, RYR1, or ZC4H2 achieved independent walking." (PMID 40443119, 2025).
Atrophy (3 papers, 2015 to 2025). Any weakening or degeneration, especially through lack of use. "These experiments tested the hypothesis that pharmacological blockade of the RyR1 in diaphragm fibers with AZ would prevent MV-induced increases in mitochondrial ROS production, protease activation, and diaphragmatic atrophy." (PMID 26849371, 2016). "Thus, our findings that RyR1 blockade did not protect against diaphragmatic atrophy during prolonged MV are not surprising, as AZ failed to prevent several known upstream mediators of VIDD." (PMID 26849371, 2016).
bleeding disorder (3 papers, 2018 to 2024). "Furthermore, animal studies have shown non-neuromuscular features such as a mild bleeding disorder and an immunological gain-of-function associated with MH/ERM related RYR1 variants raising important questions for further research." (PMID 34414986, 2021). "Implication of RyR1 in a brain disorder like ET widens this clinical spectrum beyond the neuromuscular domain, in line with reports suggesting a role of RyR1 in an increasing number of non-skeletal muscle presentations such as mild bleeding disorders and, more recently, pancreatitis." (PMID 38326582, 2024).
Cachexia (3 papers, 2017 to 2025). Severe weight loss, wasting of muscle, loss of appetite, and general debility related to a chronic disease. "These enzymes, along with thermogenic proteins (e.g., Ucp1, Sln, Ryr1 and Atp2A1) may be targetable to mitigate cachexia‐related fat loss." (PMID 40468964, 2025).
channelopathies (3 papers, 2019 to 2022). "In subject 2.1 and 2.2 focused single gene analysis comprised NGS panel for genes associated with channelopathies, Long QT syndrome, DMD, LPIN1, and RYR1 were negative." (PMID 31339582, 2020).
diabetes (3 papers, 2020 to 2023). "The abnormalities in [Ca2+]i observed in RYR1-p.163C and db/db are consistent with previous reports in malignant hyperthermia susceptible muscle cells and from experimental models and patients with diabetes." (PMID 35547584, 2022).